INS (insulin)
Diseases named in the same sentence as INS in open-access papers (continued):
Sharing a sentence is not in itself a finding about the gene and the disease.
type 1 diabetes (continued). "The lesser severity of COVID-19 observed in patients with type 1 diabetes compared to those with type 2 may be partially attributed to the general blood sugar control maintained by insulin therapy." (PMID 38399498, 2024). "Type 1 diabetes (T1D) is an autoimmune disease where the immune system mistakenly destroys insulin-producing cells in the pancreas, causing a severe lack of insulin needed to control blood sugar levels." (PMID 39195172, 2024). "The patient reported a history of maternal diabetes type 1 on insulin for the past 10 years." (PMID 39445236, 2024). "Type 1 diabetes is an autoimmune disease in which the immune system attacks and destroys the beta cells in the Langerhans islets, which are responsible for producing insulin." (PMID 38673817, 2024). "Furthermore, metformin has also been shown to reduce insulin doses in people with type 1 diabetes, which is consistent with the results of our study, but this finding was not uniformly observed in all studies." (PMID 39598003, 2024). "However, the patient had a medical history of type 1 diabetes which was being controlled with insulin injections and was also undergoing opioid-assisted treatment with sublingual buprenorphine due to a history of drug abuse." (PMID 38059982, 2024). "Mesenchymal stem cell infusion and vitamin D supplementation may have immunomodulatory actions that could prolong the preservation of residual insulin secretion in patients with type 1 diabetes (T1D)." (PMID 38790009, 2024). "Insulin therapy is a necessary treatment for type 1 diabetes." (PMID 38378741, 2024). "In some patients with MODY, insulin and C-peptide levels may be so low that they resemble those observed in patients with type 1 diabetes, with the same typical labile glucose levels." (PMID 39902162, 2024). "Therefore, we tested insulin as a cardiovascular neuromodulator therapy in an animal model of type 1 diabetes." (PMID 38794147, 2024). "Patients on oral hypoglycaemic agents may require a short course of insulin or the addition of other glucose-lowering agents, while those with type I diabetes may need adjustment to their insulin regimen." (PMID 39522614, 2024). "However, because the management of type 1 diabetes frequently involves technologies (eg, insulin pumps and continuous glucose monitoring) that pose unique challenges, it is important to study the 2 groups separately and in longitudinal studies." (PMID 38587841, 2024). "Patients with type 1 diabetes lack endogenous insulin; they are at risk of ketoacidosis if sufficient insulin is not supplied." (PMID 39458209, 2024). "Notably, a biomimetic algorithm, based on islet SPs, was extremely well adapted to regulate insulin delivery in a human in-silico model of type 1 diabetes, the UVA PADOVA TMDS." (PMID 38883608, 2024). "Therefore, consideration of starting insulin should trigger a referral to a specialist centre with expertise in initiating and managing people with type 1 diabetes on insulin." (PMID 38910151, 2024). "In type 1 diabetes (T1D), impaired insulin sensitivity may contribute to the development of diabetic kidney disease (DKD) through alterations in kidney oxidative metabolism." (PMID 39436695, 2024). "Exogenous insulin and food are the two major determinants of blood glucose in type 1 diabetes." (PMID 38257092, 2024). "Therefore, metabolomics is highly appropriate for studying the metabolic perturbation in type 1 diabetes that acutely manifests under stress (increased metabolic rate, carbohydrate oxidation, and insulin sensitivity) in exercise." (PMID 38662134, 2024). "Additional analyses of amidated GLP-1 in alpha cells and co-expression of insulin and glucagon are needed to support the hypothesis that alpha cells adapt in type 1 diabetes by acquiring beta cell identity and produce GLP-1 in islets." (PMID 39404844, 2024).
type 1 diabetes (continued). "It has been proposed that cataract formation usually occurs in the several weeks or months after the initiation of insulin treatment in type I diabetes, and insulin autoantibodies are positive within 3 months of the initiation of insulin therapy, which coincided with cataract formation." (PMID 39015537, 2024). "Several case series, observational studies, and one 7-day randomized controlled trial have demonstrated that a ketogenic diet, defined as ≤50 g of carbohydrates per day can reduce glycemic variability, HbA1c, and total daily insulin requirement in people with type 1 diabetes." (PMID 38989268, 2024). "These individuals represent a selected group of people with type 1 diabetes; nevertheless, it is expected that people treated with insulin injections may derive comparable benefits from HF and HP dietary strategies." (PMID 38257092, 2024). "However, co-transplantation of autologous ASC-derived insulin-producing cells and hematopoietic stem cells showed a better response in individuals with type 1 diabetes (T1D) as compared with a similar allogeneic regimen." (PMID 37962697, 2024). "A long clinical history of symptomatic type 1 diabetes prior to exogenous insulin supplementation (i.e., initiation of therapy) and the concomitant ketoacidosis significantly reduce the likelihood of surviving residual insulin function and, thus, the consistency of remission." (PMID 39519472, 2024). "Participants with type 1 diabetes had numerically higher insulin levels than healthy participants." (PMID 38427076, 2024). "The majority of patients had type 1 diabetes (n = 57, 95.0%); approximately equal numbers were managed with continuous subcutaneous insulin infusion (CSII) pumps vs. multiple daily injections (MDIs), whilst 88.3% (n = 53) also utilised continuous glucose monitoring (CGM)." (PMID 39519612, 2024). "CeQur simplicity by CeQur is another patchable insulin pump for type 1 diabetic patients." (PMID 39065641, 2024). "We report that virtual insulin pump initiation has a similar safety and efficacy profile as an in-office insulin pump initiation in maintaining optimal glycemia in children and adolescents with type 1 diabetes." (PMID 38745900, 2024). "Therefore, we evaluated the urinary 3-hydroxyisobutyrate association with the baseline eGDR, which is used to estimate insulin sensitivity in individuals with type 1 diabetes." (PMID 39593124, 2024). "This work should now be replicated in other prospective studies to evaluate whether the glycaemic profile predicts outcomes in people with type 1 diabetes, in particular when automated insulin delivery systems are more generalised." (PMID 38780786, 2024). "Insulin is utilized to deal with insulin-dependent diabetes or type I diabetes mellitus." (PMID 39771551, 2024). "The primary treatment method for type 1 diabetes is insulin therapy." (PMID 39063417, 2024). "Therefore, we studied the endogenous insulin secretory response to several relevant secretagogues in patients with longstanding type 1 diabetes and compared different tests for the unmasking of residual beta cell function." (PMID 38446636, 2024). "In contrast, type 1 diabetes (T1D), characterized by a total lack of insulin, is associated with an increased risk of ALS." (PMID 38791099, 2024). "Type 1 diabetes (T1D) is one of the most complex chronic conditions to manage on a daily basis, requiring constant vigilance through self-monitoring of glucose levels and moment-to-moment decision-making regarding insulin dosing." (PMID 39509700, 2024). "Since individuals who present with clinical type 1 diabetes (stage 3) often have significant residual beta cell function, they may benefit from therapies that can optimise prolongation of insulin secretion." (PMID 38910151, 2024).
type 1 diabetes (continued). "Experimental research in a rodent model of type 1 diabetes has shown that the glucagon response to insulin-induced hypoglycaemia can be enhanced by activation of key hypothalamic glucose-sensing regions, which in turn amplify the autonomic response to hypoglycaemia." (PMID 38010533, 2024). "However, in the last four decades, mounting evidence supports the adoption of more intensive insulin replacement strategies for individuals with type 1 diabetes." (PMID 39065795, 2024). "The immune-mediated destruction of insulin-producing β-cells characterizes type 1 diabetes." (PMID 39678192, 2024). "Until recently, insulin was the only pharmacotherapeutic option for type 1 diabetes (T1D)." (PMID 38675446, 2024). "The findings could also, hypothetically be explained by less exposure to hypoglycaemic episodes in people with type 1 diabetes due to improvement of insulin therapy and use of CGM, compared to earlier studies and warrants further investigation." (PMID 38376580, 2024). "In individuals with type 1 diabetes, a normal dose of insulin may be insufficient to maintain good glycemic control in the presence of tissue resistance induced by the infectious agent." (PMID 39597869, 2024). "The final sample included 1629 insulin users (39 096 person-months) with type 1 diabetes." (PMID 39141389, 2024). "The management of type 1 diabetes (T1D) necessitates lifelong insulin-replacement." (PMID 38799027, 2024). "The FDA has refused its approval in combination with insulin for the treatment of type 1 diabetes." (PMID 38338330, 2024). "There is increasing evidence that the clinical presentation of insulin dependent, type 1 diabetes in several low- and middle-income countries (LMIC) is different from the ‘classical’ presentation in affluent countries; this is particularly the case in sub-Saharan Africa (SSA)." (PMID 38348016, 2023). "In the case of type 1 diabetes, the immune system of the body mistakenly targets and eliminates the insulin-producing beta cells within the pancreas, leading to a complete shortage of insulin." (PMID 38130523, 2023). "With the aim to target non‐beta cell–specific inflammatory component, some randomized controlled trials targeting innate immune mediators [such as interleukin (IL)‐6R, tumor necrosis factor alpha [TNFα], and IL‐1] were developed to preserve insulin secretion in stage 3 type 1 diabetes." (PMID 37409229, 2023). "Out of which 9 participants withdrew consent, 4 participants were lost to follow-up, 4 participants were initiated on insulin, 1 participant was initially diagnosed and initiated on treatment by the study team, and 2 participants were later identified as latent-onset type 1 diabetics." (PMID 37561555, 2023). "However, the differences in the absolute treatment effect of insulin analogs are much more clinically and pharmacoeconomically significant in people with type 1 diabetes than apparent from phase III trials." (PMID 38089060, 2023). "For example, PhIP-Seq did not detect the known autoantigen insulin in type-1 diabetes, or citrullinated proteins associated with rheumatoid arthritis, likely due to the lack of conformational epitopes and post-translational modifications represented." (PMID 36690876, 2023). "Type 1 diabetes treatment includes the use of insulin and its analogues." (PMID 36840788, 2023). "In addition, clinical trials have reported that maintaining normoglycemia with intensive insulin regimen reduces the cardiovascular complications in type 1 diabetes." (PMID 37266028, 2023). "Type 1 diabetes mellitus (T1DM) is considered a chronic disease characterized by hyperglycemia and a broad spectrum of clinical manifestations due to an absolute deficiency of insulin secretion." (PMID 37189738, 2023). "Notably, the IgG1 and IgG4 were the most common subclass responses to both insulin autoantibodies (IAAs) and IAs in patients with type 1 diabetes and insulin-treated prediabetic patients with islet antibody positivity." (PMID 37143729, 2023).
type 1 diabetes (continued). "Similarly, the addition of sotagliflozin to insulin contributed to diabetic control in type 1 diabetes but with increased incidence of DKA." (PMID 37374037, 2023). "Initially diagnosed with type 1 diabetes, insulin was prescribed." (PMID 37864241, 2023). "The differences between Type 1 Diabetes and other autoimmune diseases could potentially be due the importance of insulin demand and beta-cell stress in Type 1 Diabetes development." (PMID 37061552, 2023). "Insulin lispro 100 units/mL Jr KwikPen® is the first insulin lispro 100 units/mL prefilled, disposable, half‐unit insulin pen that delivers 0.5–30 units in steps of 0.5 units for the treatment of Type 1 diabetes (T1D) and Type 2 diabetes (T2D)." (PMID 37715339, 2023). "An insulin device made via 3DP for patients with type 1 diabetes may be molded to the patient’s anatomy and made from a biocompatible polymer containing insulin nanoparticles." (PMID 37896366, 2023). "On the contrary, in the early stage of the type 1 diabetes mice model, taurine-conjugated bile acid could reduce insulin degradation." (PMID 36983352, 2023). "However, it is essential to note that, currently, advanced insulin pumps are only used by a small minority of people with type 1 diabetes, although this number is expected to increase." (PMID 37920192, 2023). "Most (89.7%) participants had type 1 diabetes, and 80.9% of participants used insulin pens." (PMID 37474582, 2023). "Thus, improving blood glucose control and intensive insulin therapy can reduce glomerular tissue deterioration in patients with type 1 diabetes, and the effect of blood glucose on kidney disease has the same conclusion in patients with type 2 diabetes." (PMID 36836895, 2023). "Similarly, the recently published American Association of Clinical Endocrinology (AACE) guidelines recommend automated insulin delivery systems for “many” patients with type 1 diabetes (grade A: high strength of evidence; best evidence level)." (PMID 36989019, 2023). "For patients with type 1 diabetes, basal insulin should never be omitted, as this poses a significant risk for DKA." (PMID 36789141, 2023). "Type 1 diabetes results from an autoimmune destruction of the insulin-producing beta cells." (PMID 37329450, 2023). "Results from the DiViD Intervention, a phase 2 randomized, placebo-controlled trial, showed that antiviral treatment with pleconaril and ribavirin for 6 months resulted in higher endogenous insulin production in children and adolescents with new-onset type 1 diabetes." (PMID 37789144, 2023). "Identifying children misclassified as having type 1 diabetes is therefore of great importance, as they can discontinue painful and cumbersome insulin injections, and early detection, when endogenous insulin secretion is highest, translates to a better prognosis when switching to sulfonylurea." (PMID 37798422, 2023). "Type 1 diabetes (T1D) is characterised as an autoimmune disease in which the insulin-producing pancreatic β-cells are destroyed, and type 2 diabetes (T2D) arises due to metabolic insufficiency, in which inadequate amounts of insulin are produced, and/or the actions of insulin are diminished." (PMID 37564976, 2023). "Since 1993, intensive insulin therapy has remained the mainstay of treatment of type 1 diabetes, albeit with a substantial self-care burden placed upon the person living with type 1 diabetes until the creation of advanced technologies that have eased many self-care demands." (PMID 37794113, 2023). "Insulin secretion was depleted, leading to diagnosis of fulminant type 1 diabetes." (PMID 38134115, 2023). "Finally, our enrichment analysis identified within our DMPs, relevant pathways related to type I diabetes mellitus (PTPRN2) insulin resistance (RPS6KA2) and secretion (ADCYAP1R1)." (PMID 37415231, 2023).
type 1 diabetes (continued). "Intensification of glucose-lowering therapy in type 1 diabetes includes multiple daily insulin injections, continuous subcutaneous insulin infusion, alongside continuous glucose monitoring and increasingly closed-loop insulin delivery." (PMID 37505282, 2023). "At the age of 5 years, the patient was diagnosed with type 1 diabetes; and blood glucose level was unknown, and was discharged after insulin treatment." (PMID 37974252, 2023). "Hence, it makes great sense to repair and regenerate the islets of Langerhans in type 1 diabetes patients to increase endogenous insulin production." (PMID 37663700, 2023). "The local hospital diagnosed “type 1 diabetes” and the patient was given insulin injections." (PMID 37974252, 2023). "In this context, the present results are encouraging as previous efforts to control glucose levels by an FCL approach in people with type 1 diabetes have shown insufficient performance due to the relatively slow absorption and action of insulin after SC insulin delivery." (PMID 36449375, 2023). "Strikingly, pediatric patients developing type 1 diabetes, despite carrying this protective INS variant and receiving the current standard of clinical care, showed reduced insulin autoimmunity, preserved beta cell function, higher C-peptide levels, and improved glycemic control." (PMID 36701305, 2023). "This review aims to provide an up-to-date insight from previously published literature into the characteristics of type 1 diabetes in sub-Saharan Africa, focusing on the clinical description, endogenous insulin secretion, and the contribution of autoimmunity and genetic markers." (PMID 36778553, 2023). "Type 1 diabetes occurs in the absence or insufficiency of insulin secretion." (PMID 36761194, 2023). "The hyperglycemic response against anti-TB drugs like rifampicin may enhance the requirement for insulin in type 1 diabetes patients." (PMID 37434784, 2023). "For example, a German study found the incidence in children and adolescents (< 20 years), defined as first-time insulin prescriptions, to be 44 % and 65 % higher than expected in the summers of 2020 and 2021, respectively, resulting in less seasonal variation in the type 1 diabetes incidence." (PMID 38074488, 2023). "For example, in our previous studies, we have isolated and enriched for insulin-reactive B cells in subjects with type 1 diabetes by incubating PBMCs with biotinylated insulin, followed by enrichment using anti-biotin magnetic beads and staining with a fluorescently labeled streptavidin." (PMID 37520578, 2023). "However, despite similar characteristics, those diagnosed at an older age were far less likely to be admitted to hospital at diagnosis, start insulin or be diagnosed as having type 1 diabetes." (PMID 37728732, 2023). "In type 1 diabetes, endogenous insulin production is greatly reduced." (PMID 37663700, 2023). "Finally, while insulin is the sole treatment for type 1 diabetes, there have been major advances in developing interventions to delay onset of type 1 diabetes." (PMID 37538198, 2023). "Psychological characteristics and attitudes of individuals affected by type 1 diabetes may play a significant role in influencing adherence and efficacy of Continuous Subcutaneous Insulin Infusion (CSII) therapy." (PMID 36801976, 2023). "Recurrent DKA (rDKA) remains an acute type 1 diabetes complication even in post-insulin era." (PMID 37106409, 2023). "During the natural history of type 1 diabetes, alpha cells develop dysfunction including failure of high-glucose-mediated suppression and poor response to low glucose (hypoglycaemic blindness) induced by iatrogenic insulin administration." (PMID 37488322, 2023). "Although the use of newer insulin analogues, continuous glucose monitors (CGMs) and hybrid closed-loop systems has lowered the risk, the majority of individuals with type 1 diabetes still frequently experience non-severe (<3.9 mmol/l [70 mg/dl]) hypoglycaemia." (PMID 37037948, 2023).